ANKK1 (ankyrin repeat and kinase domain containing 1)
Synonyms: SgK288; PKK2; X-kinase
Tractability: Small molecule: a high-quality ligand is known; it belongs to a druggable protein family. PROTAC: ubiquitination databases record sites on it; a small molecule that binds it is known.
Target class: TKL protein kinase group; Enzyme; Kinase; TKL protein kinase RIPK family; Protein Kinase
Safety:
Unwanted effects reported when the protein is acted on. In parentheses: how it was acted on, where the effect was seen, and who reports it.
Alcoholism (source: ClinPGx)
, or absent, increase in nicotine cravings (source: ClinPGx)
alcohol and drug dependence (source: ClinPGx)
hyperprolactinemia (source: ClinPGx)
increase in nicotine cravings (source: ClinPGx)
longer survival time (source: ClinPGx)
nicotine cravings (source: ClinPGx)
nicotine dependence (source: ClinPGx)
opioid dependence (source: ClinPGx)
prolactin response (source: ClinPGx)
quit smoking (source: ClinPGx)
shorter survival time (source: ClinPGx)
weight gain (source: ClinPGx)
Gene: Protein-coding gene on chromosome 11 (113,387,779 to 113,400,416, forward strand). Ensembl gene ENSG00000170209.
Gene Ontology:
Molecular function: protein binding; ATP binding; protein kinase activity; protein serine kinase activity; protein serine/threonine kinase activity
Biological process: regulation of cell cycle process; cellular response to retinoic acid
Cellular component: nucleus; cytoplasm
Genetic constraint (gnomAD): Loss-of-function variants: 37 observed, 35.22 expected, observed/expected ratio (o/e) 1.05, 90% interval 0.81 to 1.38. The upper end of that interval is the gene's LOEUF score, 1.38, which puts it in group 5 of 6, group 1 being the genes least tolerant of losing a copy. Missense variants: 1,019 observed, 924.08 expected, observed/expected ratio (o/e) 1.1, 90% interval 1.05 to 1.16. Synonymous variants: 415 observed, 386.78 expected, observed/expected ratio (o/e) 1.07, 90% interval 0.99 to 1.16.
Homologues: Orthologues: chimpanzee ANKK1 (87% identical), guinea pig ANKK1 (83% identical), dog ANKK1 (82% identical), rat Ankk1 (78% identical), mouse Ankk1 (76% identical), tropical clawed frog ankk1 (52% identical), zebrafish ankk1 (39% identical). Paralogues in human: RIPK4 (37% identical).
Diseases named in the same sentence as ANKK1 in open-access papers:
ANKK1 is named in the same sentence as 46 diseases in open-access papers, as found by Europe PMC text mining. Sharing a sentence is not in itself a finding about the gene and the disease. The quoted sentences say what the papers report.
Obesity (13 papers, 2009 to 2026). Accumulation of substantial excess body fat. "We also identified three genes (CROT, TSC1, RIN3) as new candidate susceptibility loci for obesity as well as three genes (ANKK1, ZNF804B, CSRNP3) and chromosome 17p11.2 as new candidate loci for MetS." (PMID 28445147, 2017). "ANKK1 is closely linked to the D2 dopamine receptor gene, and rs1800497 of ANKK1 has previously been associated with both addictive disorders and obesity." (PMID 28445147, 2017). "The A1 allele of the DRD2/ANKK1-TaqIA gene has been associated with addictive disorders, with obesity and with the performance in executive functions." (PMID 22848508, 2012). "The A1 allele of the DRD2/ANKK1-TaqIA gene has been associated with both addictive disorders and obesity." (PMID 22848508, 2012). "Interestingly, Ankk1 alters dopamine D2 receptor signaling; genetic variants with it have been associated with obesity, neuropsychiatric disorders, impulse control disorder and exercise reinforcement." (PMID 31912136, 2020). "In humans, reduction of striatal D2R expression by the TaqIA allele of the DRD2/Ankyrin repeat and kinase domain containing 1 (ANKK1) gene locus is associated with obesity, while effects of weight loss after bariatric surgery are associated with elevated striatal D2R density." (PMID 27730500, 2017). "Other genes that located outside of the MHC region, such as MAD1L1, RERE, SORCS3 and ANKK1, are associated with neuronal development and guidance of neuronal growth, transcriptional processes and other risk factors for depression, for example, obesity, smoking and abnormal physical development." (PMID 35354486, 2022). "This association of ANKK1 with MetS may be attributable to an effect of this gene on obesity." (PMID 28445147, 2017). "SIA notably did not detect positive selection at GWAS loci in the TCF7L2 gene associated with type-2 diabetes, the ANKK1 gene implicated in addictive behaviors, and the FTO gene associated with obesity." (PMID 34888675, 2022). "In addition, single nucleotide polymorphisms in three genes (CROT, TSC1, RIN3) and at four loci (ANKK1, ZNF804B, CSRNP3, 17p11.2) were implicated as candidate determinants of obesity and metabolic syndrome, respectively." (PMID 28445147, 2017). "Among individuals with the DRD2/ANKK1 haplotype (T-C-T-A) previously associated with obesity, no marked increase in effect of the SLC6A3 VNTR on obesity was observed (** = reference; OR*9 = 0.89, 95% CI 0.54–1.46; OR99 = 0.54, 95% CI 0.23–1.33, p-value for interaction = 0.62)." (PMID 19183461, 2009).
schizophrenia (10 papers, 2015 to 2024). A major psychotic disorder characterized by abnormalities in the perception or expression of reality. "Further investigation will be required to develop a better understanding of the mechanisms by which ANKK1 gene polymorphism influence the drug‐induced side effects in schizophrenia." (PMID 32383805, 2020). "In this study we investigated the association of ANKK1 rs2734849 polymorphism with antipsychotic‐induced HPRL in Russian patients with schizophrenia." (PMID 32383805, 2020). "The functional polymorphism rs2734849 in the ANKK1 gene was associated with HPRL in patients with schizophrenia." (PMID 32383805, 2020). "Considering rs1800497 of the DRD2/ANKK1 locus, impaired selective attention (assessed by Stroop-PI) is associated with schizophrenia more than genetics." (PMID 28085950, 2017). "Data on linkages or associations between the ANKK1 locus and schizophrenia vary among different ethnicities." (PMID 26114114, 2015). "Limited research has assessed associations between schizophrenia and genetic variants of the ankyrin repeat and kinase domain containing 1 (ANKK1) and lymphotoxin-alpha (LTA) genes among individuals of Middle Eastern ancestry." (PMID 26114114, 2015). "A SNP residing in the coding region of ANKK1 (rs1800497, commonly known as TaqIA SNP) has been previously associated with alcoholism, schizophrenia and eating disorders, although it is unclear whether this SNP exerts its effect via DRD2 or ANKK146." (PMID 37117178, 2023). "ANKK1 is dominantly expressed in brain, which is consistent with the polymorphism Taq1A that leads to ANKK1 reduced stability being associated with schizophrenia." (PMID 36263437, 2022). "The results of this study indicate that the prevalence of antipsychotic‐induced HPRL in Russian patients with schizophrenia is higher in carriers of rs2734849*С allele of ANKK1 gene whereas allele rs2734849*T of ANKK1 gene has a protective effect against antipsychotic‐induced HPRL in this sample." (PMID 32383805, 2020). "The preliminary epigenetic findings suggest that methylation levels at CpG site 387 of ANKK1 may be associated with the treatment response to aripiprazole in patients with schizophrenia." (PMID 32383805, 2020). "Ankyrin repeat and kinase domain-containing protein 1 (ANKK1), is a protein of unknown function that is specifically linked to neuropsychiatric disorders with impaired dopamine signalling, including schizophrenia, addiction, Tourette syndrome and ADHD25." (PMID 29391579, 2018). "The genetic phenomenon of association with the TaqIA ANKK1 SNV, however, goes beyond addictions to other psychiatric illnesses such as schizophrenia, eating disorders, and some childhood behavior disorders." (PMID 39409035, 2024). "In this study, we investigated the association between functional polymorphism rs2734849 in ANKK1 gene and antipsychotic‐induced HPRL in Russian patients with schizophrenia from the population of Siberia." (PMID 32383805, 2020). "We have previously reported a strong association between schizophrenia and various polymorphisms within the DRD2/ANKK1 locus, including rs1800497 in the ANKK1 gene, including rs2242592 in the intergenic region and rs6277 in DRD2 gene." (PMID 28085950, 2017). "The main finding of this exploratory study involves rs6275 and rs2242592 of the DRD2/ANKK1 locus and Stroop Color-Word in schizophrenia." (PMID 28085950, 2017). "We have presented the first association study investigating the ANKK1 rs1800497 (T>C) and LTA rs909253 (A>G) SNPs in an Egyptian sample of patients with schizophrenia." (PMID 26114114, 2015). "In the present case-control study, we focus on polymorphisms of ANKK1 and LTA as possible risk factors for schizophrenia." (PMID 26114114, 2015). "The ANKK1 CpG site 387 is a target of the CCCTC-binding factor that might potentially alter the dopamine D2 density and the methylation of ANKK1 might affect dopaminergic transmission in schizophrenia treatment." (PMID 36979236, 2023).
schizophrenia (continued). "Our results support the involvement of ANKK1 rs2734849 into pathogenesis of antipsychotic‐induced HPRL in schizophrenia, although the underlying molecular mechanisms are not clear." (PMID 32383805, 2020). "Specifically, we hypothesized that the C allele within the rs1800497 SNP of ANKK1 and the G allele within the rs909253 SNP of LTA may affect vulnerability to schizophrenia among Egyptian cases." (PMID 26114114, 2015). "Furthermore, methylation of ANKK1 may affect dopaminergic neural transmission in the treatment of schizophrenia, and may influence treatment response." (PMID 32383805, 2020). "Despite the fact that the rs1800497 SNP is localized to the ANKK1 gene, it seems to be in linkage disequilibrium with several DRD2 genetic variants, which could potentially explain a dopaminergic role in the etiopathogenesis of schizophrenia." (PMID 26114114, 2015). "Three SNPs, i.e., rs1799732 and rs6276 located within DRD2, and rs1800497 within ANKK1, were identified in the DNA samples of 198 schizophrenia probands, including 103 patients with deficit (DS) and 95 patients with non-deficit schizophrenia (NDS)." (PMID 32565876, 2020). "A comparison between schizophrenia patients with and without HPRL revealed significantly higher frequency of the C allele of the polymorphic variant rs2734849 in the ANKK1 gene in patients with HPRL as compared to the patients without it (χ2 = 3.70; p = .05; odds ratio [OR] = 1.30 [0.99–1.69])." (PMID 32383805, 2020).
alcohol dependence (9 papers, 2008 to 2023). Physical and psychological dependence on alcohol. "The association between the SNP of the dopaminergic D2/ANKK1 gene (rs1800497), the serotonin-related polymorphism in the 5HT2A gene (rs6313), and impulsivity, cognition, and alcohol misuse in young adults was studied." (PMID 37509436, 2023). "Munafò also supported association of the individuals possessing the A1 allele of the TaqIA ANKK1 polymorphism with alcohol dependence." (PMID 25415204, 2014). "In fact, TaqIA variants change the amino acid in the ANKK1/X-kinase gene, and might confer functional biological consequences in alcohol dependence." (PMID 19506733, 2008). "Also, in a recent association study, COGA researchers have found that alcoholism association with the DRD2 region actually may be the result of an association with the nearby ankyrin repeat and kinase domain containing 1 (ANKK1) gene." (PMID 23584748, 2008). "Another study analyzed the involvement of DRD2 and ANKK1 in 219 Caucasian families with alcoholism, using data collected as a part of the Collaborative Study on the Genetics of Alcoholism (COGA)." (PMID 32260442, 2020). "In this review, we begin by presenting the actual status of the genetic association between the ANKK1 TaqIA SNV and alcoholism." (PMID 32260442, 2020). "Of note, the ANKK1-rs1800497-T allele has been previously associated with attention deficit hyperactivity disorder (ADHD) and with deficits in sustaining attention observed in individuals with alcohol dependence." (PMID 35935430, 2022). "In addition to past associations with ND, ANKK1 and DRD2 have been associated with other neurobehavioral traits including alcohol dependence, reinforcement learning, working memory, and executive function." (PMID 23691092, 2013).
depression (8 papers, 2012 to 2025). "It has been demonstrated that PSEN2 knock-in mice exhibit severe depressive behavior, and PCDH9 and ANKK1 have also been reported as risk genes for depression." (PMID 40075226, 2025). "Likelihood of increased smoking level rose 2-fold with each additional DRD2/ANKK1 rs1800497 minor allele, with a pronounced association among adolescents with depression symptoms." (PMID 24927283, 2014). "Further, the association between smoking cessation and lifetime depression was significantly modified by DRD2/ANKK1 rs1800497 genotype." (PMID 24927283, 2014). "The DRD2/ANKK1 Taq1A polymorphism (rs1800497) affects striatal D2 receptor binding, with the A1 allele associated with reduced binding in healthy individuals but increased binding in depression." (PMID 41373485, 2025). "The seven positively selected depression-associated genes we identified in the human lineage are involved in brain development (PSEN2, ANKK1, PCDH9) and immunity (STAU1 and LYRM4), as highlighted in our results." (PMID 40075226, 2025). "Interestingly, this same gene along with ANKK1 was recently confirmed by a meta-analysis of the three largest GWAS on depression as having a key role in MDD." (PMID 34201295, 2021).
Anxiety (7 papers, 2008 to 2025). Intense feelings of nervousness, tension, or panic often arise in response to interpersonal stresses. "The other allele that influences D2 receptor availability in the striatum is located in the ANKK1 gene, and can be associated with the anxiety symptoms occurring from early childhood similarly to the A allele of rs1076560." (PMID 32365807, 2020). "We found a relationship of anxiety symptoms lasting from early childhood with the influence on the availability of D2 in the striatum, which in turn is conditioned by the A1 allele of the ANKK1 gene." (PMID 31948125, 2020). "The absence of an effect of the acute psychosocial stressor on the ANKK1 TaqIA-impulsivity relationship, despite a significant increase in subjective anxiety, underscores the importance of the ANKK1 main effect on impulsivity." (PMID 19025655, 2008).
nicotine dependence (6 papers, 2011 to 2020). Physical and psychological dependence on nicotine. "The DRD2 gene and the adjacent ANKK1 gene have been linked to D2R deficits, nicotine dependence, and reward sensitivity." (PMID 24065931, 2013). "We hypothesized that smokers carrying at-risk nAChR, ANKK1, or D2 receptor alleles (i.e., alleles previously linked to smoking behavior and nicotine dependence) would be more likely to be in the IRS− group, as assessed by ERP to motivational stimuli, compared to those without these alleles." (PMID 24065931, 2013). "In a large male Chinese Han smokers sample (n: 2.616 patients), the study of the NTAD cluster identified two missense ANKK1 SNVs (rs11604671, rs2734849) and one intronic DRD2 SNV (rs4648317) associated with nicotine addictions." (PMID 32260442, 2020). "Other studies of NTAD cluster identified in the African-American and European-Americans/African-Americans pooled sample the association between the ANKK1 rs2734849 SNV and nicotine dependence." (PMID 32260442, 2020). "This study provides preliminary results regarding the effect of the SLC6A3 VNTR, ANKK1/DRD2 TaqIA, and CYP2A6*4 polymorphisms on smoking cessation and nicotine dependence in a Japanese population." (PMID 25526961, 2014). "The present study also examined the effect of smoking history (age at which the participant began smoking and duration of smoking) on the association between SLC6A3, ANKK1/DRD2, and CYP2A6 polymorphisms and nicotine dependence." (PMID 25526961, 2014). "This study examined whether functional polymorphisms in SLC6A3, ANKK1/DRD2, and CYP2A6 affect smoking cessation and nicotine dependence in a Japanese population." (PMID 25526961, 2014). "For instance, in nicotine addiction, family-based association studies in Caucasian and African American affected sib-pairs, showed strong and consistent evidence of an association with the TTC12 (rs2303380, rs2282511) and ANKK1 (rs4938012, rs4938013, rs4938015) genes." (PMID 32260442, 2020). "The ANKK1 rs1800497 has been linked to nicotine dependence in some, but not all, studies." (PMID 24065931, 2013). "We found that current smokers with the SLC6A3 10r/10r genotype were more likely to have low nicotine dependence, based on HSI analysis, although the genotypic differences between current and former smokers were not significant for any of the SLC6A3, ANKK1/DRD2, and CYP2A6 polymorphisms tested." (PMID 25526961, 2014). "We found that current smokers with the 10r/10r genotype were more likely to have low nicotine dependence based on HSI analysis, although the genotypic differences between current and former smokers were not significant for any of the SLC6A3, ANKK1/DRD2, and CYP2A6 polymorphisms." (PMID 25526961, 2014).
bruxism (2 papers, 2023 to 2025). Excessive clenching of the jaw and grinding of the teeth. "SNP in the DRD2 gene was associated with bruxism and its circadian phenotype, whereas SNPs in ANKK1 and COMT were found to be associated with circadian phenotypes of bruxism." (PMID 37252006, 2023). "Variations in genes like 5HTR2A, DRD2, DRD3, ANKK1, COMT, MMP9, ACTN3, and ANKK1 are linked with the susceptibility to Bruxism." (PMID 40291793, 2025).
epilepsy (2 papers, 2018 to 2024). A brain disorder characterized by episodes of abnormally increased neuronal discharge resulting in transient episodes of sensory or motor neurological dysfunction, or psychic dysfunction. "Furthermore, a cohort study involving 212 Han Chinese patients with epilepsy treated with VPA identified associations between weight gain and polymorphisms in the leptin receptor (LEPR) and ankyrin repeat kinase domain containing 1 (ANKK1) genes." (PMID 39539630, 2024).
metabolic syndrome (2 papers, 2017 to 2025). A cluster of metabolic risk factors for CARDIOVASCULAR DISEASES and TYPE 2 DIABETES MELLITUS. "Lastly, from the four male-specific MDD/metabolic syndrome pleiotropic regions we identified one possible causal risk variant which mapped to the gene ANKK1." (PMID 40858613, 2025).
opioid dependence (2 papers, 2015 to 2024). "DRD2/ANKK1 TaqIA polymorphism is associated with opioid dependence risk, when individual is diagnosed with phlegm syndrome." (PMID 26138154, 2015). "Another innovative aspect of this review is the demonstration that the homozygous TT mutant of the ANKK1 TaqI A polymorphism rs 1800497 may be a factor in increased risk of opioid dependence." (PMID 39595582, 2024). "The innovation of this review is to show that the homozygous TT mutant of the ANKK1 TaqI A polymorphism rs 1800497 may be a factor in increased risk of opioid dependence." (PMID 39595582, 2024). "In recent years, The meta-analysis suggested that DRD2/ANKK1 TaqIA polymorphism might be associated with opioid dependence risk." (PMID 26138154, 2015).
Parkinson disease (2 papers, 2021 to 2022). A progressive degenerative disorder of the central nervous system characterized by loss of dopamine producing neurons in the substantia nigra and the presence of Lewy bodies in the substantia nigra and locus coeruleus. "RIPK5/ANKK1 polymorphisms are associated with neuropsychiatric disorders, including Parkinson’s disease." (PMID 36263437, 2022).